IL7 (interleukin 7)
Diseases named in the same sentence as IL7 in open-access papers (continued):
Sharing a sentence is not in itself a finding about the gene and the disease.
tumor (continued). "Interestingly, genetic modification of MSCs to over-express IL-7 and IL-12 may shift the chronic inflammatory profile in the tumor microenvironment to favorable Th1/Th17 for an acute CART cell response by improving and amplifying the antitumor CART cell response." (PMID 34202907, 2021). "In 2018, Keishi Adachi team constructed co-expressing IL-7 and CCL19 CAR-T cells, and demonstrated excellent tumor-killing activity in multiple solid tumors." (PMID 34386015, 2021). "Surprisingly, they found that expression of IL-7 and CCL19 significantly improved T-cell infiltration and survival of CAR-T cells in mouse tumors, enhancing the anti-tumor activity against solid tumors." (PMID 34925323, 2021). "Another recent study used MSCs as vehicles to deliver immuno-modulatory proteins, IL7 and IL12, to improve the anti-tumor impact of CAR T cells in a transplant tumor model." (PMID 34200425, 2021). "While long-term T cell culture in IL-2 drives terminal differentiation, the common γ-chain cytokines IL-7 and IL-15 have been reported to promote a central memory T cell (TCM cell) phenotype enabling superior persistence and in vivo tumor control upon ACT." (PMID 33156338, 2021). "Various immunocytokines have been combined with additional unconjugated cytokines such as IL-7, IL-2, Fms-like tyrosine kinase-3-ligand (Flt3-L), and IFN-γ to show enhanced tumor control and the activation of the immune response." (PMID 33803078, 2021). "The IL-7-mediated JAK1/STAT5 pathway bypasses BCR/ABL signals, protecting tumor cells from imatinib (IM) and nilotinib (NI) in a BCR/ABL-independent way." (PMID 34095111, 2021). "IL‐7 and CCL19 are crucial for T‐cell zone maintenance in lymphoid organs and T cells expressing IL‐7 and CCL19 exhibited great tumor clearance capacity." (PMID 34766142, 2021). "Improved tumour suppression and prolonged survival after combined treatment with CAR-T cells and IL7/IL12-expressing MSCs, co-inoculated with the tumour cells." (PMID 34769211, 2021). "Adachi and colleagues also showed that IL-7 and CCL19 co-expressing CAR-T cells become differentiated into central memory CAR T cells with superior tumor-infiltrating capacity and higher persistence rate in a P815-hCD20 (mastocytoma) mouse model." (PMID 34721401, 2021). "Further, IL-7 treatment can enhance long-term tumor antigen-specific CD8 + T cell response and greatly prolong the survival of tumor patients." (PMID 32381120, 2020). "Combined expression of IL-7 and CCL21 significantly improved survival and infiltration of CAR T cells and DCs in tumor." (PMID 33292660, 2020). "Our results suggest that tumor-induced arrest of DN2 T cells in the thymus is correlated with a significant increase in il-10 transcription and a coordinated reduction in il-7 and il-15 transcription." (PMID 32582141, 2020). "CAR-T cells expressing IL-7 (for enhanced proliferation and survival) and CCL19 (for chemoattraction), called 7 × 19 CAR-T cells, enhanced anti-tumor activities and increased the infiltration of dendritic cells and T cells in the TME." (PMID 32731404, 2020). "In order to alter the cytokine profile in the tumor tissue we modified the MSCs by genetic engineering to release IL7, IL12, and both IL7 and IL12, respectively." (PMID 32260097, 2020). "MSCs were engineered to release both IL7 and IL12 in order to shift the chronic inflammatory profile in the tumor tissue into a more favorite one for an acute CAR T cell response." (PMID 32260097, 2020). "Based on the IL7 pathway, signaling cytokine receptor was established to improve the effects of the CAR-T therapy in preclinical tumor models." (PMID 33102231, 2020). "Hereby, IL7 will improve persistence of CAR T cells and other cytotoxic lymphocytes in the periphery and the tumor tissue whereas IL12 will directly boost anti-tumor cytotoxicity as demonstrated in this report." (PMID 32260097, 2020).
tumor (continued). "The result claimed that IL7 and IL21 were superior to IL2 and IL15 in enhancing tumor eradication, although IL2 and IL15 established increased effector functions." (PMID 33381115, 2020). "IL-7 and CCL19 expression in CAR T cells improves immune cell infiltration in the tumor, where both recipient conventional T cells and administered CAR T cells generated memory responses against tumors." (PMID 33292660, 2020). "Accordingly, cytokines like IL-2, IL-7, IL-15, and IL-21 are fundamental both for generation of the ACT cell products and to increase the efficacy and the duration of the anti-tumor response in vivo." (PMID 32973794, 2020). "The study also showed that lymphodepletion before CAR T cell injection decreased efficacy, suggesting that IL-7 and CCL19 recruited endogenous anti-tumor TILs as well." (PMID 30804938, 2019). "As compared to EC and GC, tumor-adjacent tissue from CRC patients had, respectively, 2.3- and 2.8-fold higher concentration of IL-7." (PMID 31185636, 2019). "We found ten potential prognostic genes, including eight tumor suppressor and/or driver genes (VEGFA, CCND1, BAX, IL7R, SHC1, FLT1, IL7, and JAK3), as well as two chemokines (CXCL9 and CXCL10)." (PMID 31661791, 2019). "Interestingly, our results showed that IL-7 overexpression in advanced cancers was not caused by increased cytokine concentration in tumors, but rather by its decreased concentration in noncancerous tissue adjacent to the tumor." (PMID 31185636, 2019). "It was reported that the central memory T cells showed higher anti-tumor toxicity than the effector memory T cells in vivo, and the stimulation by combined anti-CD3, anti-CD28, IL-7 and IL-15 was reported to improve T cell specific cytotoxicity." (PMID 31044002, 2019). "When all tumor samples were evaluated together the correlation of GZMH, ABL1, IL-7, LY9, IL-12, SCAMP3, and CD244 were highly significant (p < 1 × 10−6)." (PMID 29587383, 2018). "When in combination with liver-specific IL-12 or IL-7, OXP increased CD8+/ Treg cell ratio in murine metastatic colon cancer model, reducing immune suppressive response and further enhancing anti-tumor immune response." (PMID 29416788, 2018). "In Treg-replete (phosphate-buffered saline-injected) or Treg-depleted (DT injected) tumor-bearing (day 12) DEREG mice, 1:1 mixture of congenic IL-2(CD45.1) and IL-7(CD45.2) effectors was intratumorally injected." (PMID 28496990, 2017). "Briefly, IL-12, IL-17, GM-CSF, MIP-1α, IL-5, IFN-γ, IL-1Rα, IL-7, IP-10, IL-2R, IL-4,IL-15,MIP-1β levels were higher in the inflammation group and kept relative lower level in healthy and tumor groups." (PMID 28977824, 2017). "However, the IL-7 therapy might enhance tumor lymphangiogenesis and metastatic spread in cancers." (PMID 28036019, 2016). "For example, Interleukin-7 (IL-7) is a potent growth, activation and survival factor for CD8+ T cells that can be used to improve virus- and tumor-specific CD8+ T cell responses." (PMID 27447484, 2016). "Prophylactic vaccination with IL-21 and IL-7 co-expressing B16F10 cells and tumor challenge were repeated in wild-type, CD4 knockout and CD8 knockout (KO) mice in this study." (PMID 27571893, 2016). "To assess if combination therapy-improved mouse survival also depends on IL-7 and IFN-γ signalling in T cells, we followed long-term survival of CD45.1 tumour-bearing mice that were infused with WT, Ifngr1−/− or Il7r−/− total T cells." (PMID 27498556, 2016). "Intranodal lymphatic sinuses are also greatly influenced by CCR7-CCL19/CCL21, CXCL12/CXCR4, S1P, IL-7, IFN-γ, integrin α4β1, and TGF-β in tumor microenvironment." (PMID 28036019, 2016). "Taken together, we conclude that combination therapy potently reverses immunosuppression and eradicates tumours via an intricate interplay between IFN-γ/IFN-γR and IL-7/IL-7R pathways." (PMID 27498556, 2016). "Combination therapy-mediated tumour eradication requires presence of T cells and an intact loop of IFN-γ and IL-7 signalling in T cells." (PMID 27498556, 2016).
tumor (continued). "Taken together, these results corroborate our above findings in KO mice that IL-7 and IFN-γ signalling in T cells modulate immune responses and tumour inhibition by combination therapy." (PMID 27498556, 2016). "Culturing CD3/CD28-CAR-T in the presence of IL-7 and IL-15 gave the best effector activity while retaining a stem/memory against GD2 tumor antigen." (PMID 26999211, 2016). "Significant inhibition of the tumor growth was observed in the groups treated with both PAP-GMCSF alone and with the co-administration of PAP-GMCSF, -IL2, -IL4 and -IL7." (PMID 25632844, 2015). "IL-7, when given in conjunction with OXP, increased the anti-tumor effect in vivo compared to PBS, IL-7 and OXP groups respectively (P<0.001, n = 6∼7)." (PMID 24465710, 2014). "The results were expressed as mean ± S.E. The results clearly demonstrated that the combination of IL-7 and OXP achieves the best therapeutic effect, as measured by anti-tumor effect." (PMID 24465710, 2014). "The antitumor effect of combining IL-7 and OXP correlated with a marked increase in the number of tumor-infiltrating activated CD8+ T cells and a marked decrease in the number of regulatory T (Treg) cells in spleen." (PMID 24465710, 2014). "Tumor RTL and T/N RTL ratio correlated positively with three of the cytokines (IL-7, IL-8 and IL-10), whereas TA correlated inversely with IL-7 and IL-8." (PMID 23383336, 2013). "IL-7 was shown to increase proliferation, migration, and tube formation of endothelial cells in vitro and the growth of LYVE-1+ vessels in tumor-containing matrigel plugs in vivo." (PMID 22946011, 2012). "Our results show that endothelial and/or stromal cells within the tumour express higher levels of mouse-specific cytokines (MCSF, IFNG, IL5, IL7 and CXCL9) in VEGFA165 tumours compared with control tumours." (PMID 22045186, 2011). "In contrast, Th1 cytokines IL-2 and IL-7 are potent stimulators of T-cell cytotoxic activity and of memory CD8+ T cell survival, respectively, both of which are critical for effective tumor immunotherapy." (PMID 19956757, 2009). "These factors, in conjunction with IL-7, engage with PD-L1 via the JAK-STAT/PI3K-Akt cascades, thereby establishing a complex network of signaling pathways within the stroma and vascular component of the tumor." (PMID 41597220, 2026). "In this analysis, all CAR T cells displayed complete elimination of tumor cells for three rounds (in the condition without addition of cytokines IL7/15)." (PMID 41037684, 2026). "IL-7 restores CD8+ T cell function by reducing exhaustion markers such as PD-1 and simultaneously promoting the expansion of Tregs, which can suppress anti-tumor immunity." (PMID 41596598, 2026). "Moreover, studies have shown that CAR-T cells engineered to co-secrete IL-7 and CCL19 (7 × 19 CAR-T cells) exhibit superior tumor suppression, proliferation capacity, and tumor infiltration in HCC xenograft models." (PMID 40051497, 2025). "All CAR constructs used in this study are based on a second-generation CAR designed with 4-1BB as an intracellular costimulatory domain, and all expanded or quiescent CAR T cells were conditioned with human IL-7 and IL-15 post-EP or -LNP and prior to coculture with tumor cells." (PMID 40896578, 2025). "The vaccine efficacy was also tumor-specific in the therapeutic settings since the EL4-LX/IL-7 vaccine did not work against antigenically unrelated B16-F10 tumors." (PMID 40957993, 2025). "Data indicate that introducing IL-7 into B7-H3 CAR-7 cells (B7-H3 CAR-7/IL-7), may effectively kill CMA cells in the organoid model and exhibit sustained anti-tumor effects." (PMID 40271075, 2025). "For example, the inverted cytokine receptor (ICR) of IL-4/IL-7, composed of the IL-4R extracellular domain and the IL-7R intracellular domain, reduces IL-4’s inhibitory effect on CAR-T cells, promoting T cell proliferation and enhancing anti-tumor activity." (PMID 39958351, 2025).
tumor (continued). "Taken together, our results demonstrate that C.P cells can be engineered to efficiently secrete IL-7, which is produced in an antigen stimulation-dependent manner without compromising the antigen specificity or anti-tumor function of the CAR." (PMID 40808942, 2025). "Similar findings have been reported with dual armoring with IL-7 and CCL21, another CCR7 ligand, which also promoted T-cell and DC recruitment, increased central memory phenotype T-cells, and improved tumor control in an antigen-heterogeneous tumor model." (PMID 41019052, 2025). "Furthermore, the combination of IL-7 and IL-15 plays a crucial role in increasing the number of CD8+CD45RA+CCR7+ within the CAR T cell products, enhancing persistence and anti-tumor activity in preclinical models." (PMID 41346587, 2025). "Furthermore, viral expression of IL-7 alone, and especially with other cytokines, within tumors improves the antitumor efficacy of CAR-T cell immunotherapy, autologous tumor cell vaccines, and ICI treatment." (PMID 40957993, 2025). "Tumor growth inhibition was more pronounced with intratumoral Ad.IL-7/B7.1 treatment compared to Ad.βgal, leading to 70% (7/10) tumor-free long-term survivors in the Ad.IL-7/B7.1 group, but there were no survivors in the Ad.βgal group." (PMID 40957993, 2025). "While IL-7 expression alone does not achieve complete tumor eradication, it significantly enhances vaccine efficacy associated with cytotoxic T cell responses." (PMID 40957993, 2025). "Additionally, IL-7 supports T cell survival and homeostasis, while CXCL9 plays a role in effector T cell recruitment to the tumor." (PMID 40630200, 2025). "Moreover, the combination of chemokine receptor (including CCR2b and CXCR5) and IL-7 armoring has been demonstrated to boost CAR T-cell expansion and anti-tumor activity in immunodeficient mouse tumor models." (PMID 41019052, 2025). "Furthermore, the combination of C8A8 with IL-7-CAR-T cells significantly increased IL-2 and IFN-γ secretion and demonstrated strong anti-tumor activity." (PMID 41450878, 2025). "Further, serum cytokine levels, such as MCP-1, GM-CSF, IL-2, IL-6, IL-7 and IL-18, correlated with tumor growth independent of various treatments." (PMID 40386779, 2025). "To assess this, we cultured C.M7R cells in conditioned medium harvested 48 hours after stimulating C.P7 cells or C.P (control lacking IL-7) with irradiated CAPAN1 tumor cells at E:T of 1:1." (PMID 40808942, 2025). "Consequently, the combination of IL-7 and C8A8 can synergistically enhance the anti-tumor activity of CAR-T cells, improving therapeutic efficacy." (PMID 41450878, 2025). "Irradiated B16-F10 cells loaded with non-lytic NDV LX strain expressing IL-7 (i.e., B16-LX/IL-7) were utilized as an autologous tumor cell vaccine." (PMID 40957993, 2025). "The authors concluded that the lack of efficacy against non-transplanted tumors was not due to the type or location of the tumor or limited adenoviral gene (IL-7/B7.1) transduction efficiency." (PMID 40957993, 2025). "Accordingly, the interaction between IL-7/IL-12-overexpressing MSCs and CAR T cells improved proliferation of CAR T lymphocytes, reduced activation-induced cell death, and increased their cytotoxicity against tumor cells." (PMID 40643499, 2025). "Our results demonstrate that nonspecific CD8+ T cells expanded with IL-7 can accumulate in tumor tissue, despite tumor-induced T cell sequestration." (PMID 40244705, 2025). "Interleukin-7 (IL-7) has been identified as a potent enhancer of T-cell proliferation and maturation, promoting the expansion of stem central memory (SCM) and central memory (CM) T cell subsets, thereby enhancing anti-tumor activity." (PMID 41450878, 2025). "Additionally, experiments using engineered CAR-T cells co-expressing IL-7 and CCL21 demonstrated enhanced anti-tumor efficacy, attributed to the increased survival and infiltration of both CAR-T cells and DCs." (PMID 39861713, 2025).
tumor (continued). "Tumor type segregation of correlation analysis showed STS tumor growth correlated significantly with increased serum levels of GM-CSF, IL-2, IL-6, IL-7, IL-18 & MCP-1, whereas increased circulatory CD4+ and CD8+ T cells numbers correlated with STS tumor regression with CPMV treatment." (PMID 40386779, 2025). "The viral co-expression of IL-7 and IL-12 in one tumor alters the immune status of non-injected tumors and significantly regresses non-injected tumors, suggesting a strong induction of whole-body antitumor immunity, essential for targeting metastatic diseases." (PMID 40957993, 2025). "This IFN-γ response was tumor-specific, as splenocytes harvested from B16-LX/IL-7-treated mice efficiently killed B16-F10 cells but not antigenically unrelated EL-4 cells." (PMID 40957993, 2025). "Intratumoral administration of TILT-517 in an immunocompetent subcutaneous HapT1 pancreatic cancer model in Syrian hamsters significantly controlled tumor burden compared to the Ad5/3-E2F-d24 control lacking IL-7 expression." (PMID 40957993, 2025). "Another approach to harnessing IL-7 signaling has been to incorporate a portion of the IL-7 receptor-α intracellular domain into the CAR structure itself, which was demonstrated to enhance T-cell proliferation and improve tumor control." (PMID 41019052, 2025). "No statistically significant increase in tumor reduction was found when comparing IL7 alone with the untreated group, demonstrating the importance of RT even in hot, virally mediated tumors." (PMID 38554147, 2024). "IL-7 promotes the proliferation as well as increases the toxicity of CAR-T, and therefore, IL-7 with CAR-T cells may improve their efficacy against solid tumours and hold the promise of achieving the complete eradication of tumour cells." (PMID 38675377, 2024). "Compared with the Normal group (normal mice without tumor cell inoculation), the expression level of antiinflammatory factors IL‐7, IFN‐γ, and IL‐12 in the Model group were significantly reduced (P < 0.05), and the GCP‐treated group reversed this trend." (PMID 38604998, 2024). "Furthermore, dex elevated IL-7Rα expression, enhancing responsiveness to IL-7 and consequently improved CAR T cells' anti-tumor activity." (PMID 38140726, 2024). "CD127- cells, lacking the ability to receive IL-7 signals, result in immune cells becoming inactive or ineffective in the tumor microenvironment, leading to immune tolerance." (PMID 38566827, 2024). "Additionally, CXCR5 and IL-7 co-expression enhanced CAR-T cell numbers, cytokine release, and survival in implanted tumor tissues compared to conventional CAR-T cells." (PMID 39450160, 2024). "By supplementing IL-7 during the in vitro expansion of CAR-T cells, constructing CAR-T cells that express IL-7 or IL-7R, or treating mice with modified IL-7 following CAR-T infusion, the persistence and anti-tumor efficacy of CAR-T cells can be significantly enhanced." (PMID 39906740, 2024). "Although we expected a substantial overlap of tumor-specific clones between individual mice, there was no clonal overlap between control and IL7-treated mice." (PMID 38424167, 2024). "The secreted cytokines IL-7, IL-12, IL-15, or IL-18 not only enhance the survival capacity of CAR–T cells and augment their cytotoxic activity but also attenuate the immunosuppressive tumor microenvironment." (PMID 39220130, 2024). "Notably, cytokine mRNA triplet with 3:1:1 mass ratio of IL-12, IL-7, and IFN-α exhibited superior anti-tumor activity, with 93.84% TGI at day 18 after the first treatment and 80% survival rate at the end of the study." (PMID 39290693, 2024). "Similarly, the expression of IL-7 and CCL19 in CAR-GPC3 T cells can promote T cell survival and tumor infiltration, leading to stronger tumor suppression compared to traditional CAR-T cells in xenograft and PDX models." (PMID 38679698, 2024).